FOXP3 (forkhead box P3)
Diseases named in the same sentence as FOXP3 in open-access papers (continued):
Sharing a sentence is not in itself a finding about the gene and the disease.
infection (continued). "In order to study the contribution of CD4 T cells to Foxp3+ and GZMB+ expression, we analyzed CD4-GZMB+ and CD4-Foxp3+ T cell counts according to the histological distribution, distinct infection status and latency profiles." (PMID 38273012, 2024). "While less frequently studied than CD4+ Treg, FoxP3+ as well CD8+ Treg can also be induced by various infections." (PMID 39140728, 2024). "Different sources of miRNAs inhibit Foxp3 expression during T. gondii infection, demonstrating the complexity of the infection process of this parasite." (PMID 38741041, 2024). "We also examined the frequency changes of CD3+CD4+Foxp3+ Tregs in periphery blood after ASFV CADC_HN09 infection." (PMID 38419627, 2024). "Natural regulatory (Foxp3+CD25+CD4+) T cells regulate the production of proinflammatory cytokines during infection, with Foxp3+CD25+CD4+ Tregs promoting IL-10 production." (PMID 39582867, 2024). "The evaluation of mRNA transcript associated with Tregs (CD25, FoxP3, CTLA-4, and IDO), after experimental infection of beef calves with low (LV) or high (HV) virulence BVDV have also been studied." (PMID 38596123, 2024). "The mRNA levels of ROR-γt in intestinal tissues were the highest on the second day after infection, and the mRNA levels of Foxp3 were the highest on the third day after infection, with statistically significant differences (P < 0.01)." (PMID 38727214, 2024). "The FoxP3+level was further decreased significantly to 85%, p < 0.02 at 12 h compared to 6 h post infection." (PMID 36707891, 2023). "We observed that the frequency of CD4+FoxP3+ bTreg cells was initially low during the acute phase of infection (i.e., day 7 post prime-CNS boost), but this fraction increased within the brain by day 30 post prime-CNS boost." (PMID 37192971, 2023). "Limited studies in experimental allergic encephalitis (EAE) models demonstrated that prior infection with Hp induced Foxp3+Treg cell upregulation and inhibition of MOG specific Th1 and Th17 responses." (PMID 37304259, 2023). "Overall we noticed a significant decrease in FoxP3+ level at later time points compared to initial time points post infection." (PMID 36707891, 2023). "SBCT or VMT more potently inhibited the expression of FOXP3 and IL-17 in GV infection, which are involved in adaptive immunity." (PMID 36941732, 2023). "A significant more than 40%, p = 0.0021 decrease in FoxP3+level at 6 h was noticed compared to 3 h post JEV infection." (PMID 36707891, 2023). "In a mouse model study of infection with respiratory syncytial virus, Foxp3+ Tregs were shown to significantly accumulate in alveolar spaces and lower immunopathology of the lung by modulating the CD8+ T cell response during infection." (PMID 37833265, 2023). "The regulatory cells are characterized by the expression of the transcription factor Foxp3, thus constituting a unique subpopulation that inhibits the immune response and thus checks the exacerbation of inflammation during infection." (PMID 38069174, 2023). "Regulatory T cells (Tregs) expressing the transcription factor Foxp3 are considered central to restoring immune homeostasis during infection and preventing immune overactivation." (PMID 37833265, 2023). "The FoxP3+ level was further decreased significantly to 36%, p < 0.04 at 12 h compared to 6 h post infection." (PMID 36707891, 2023). "At this location, regulatory immune mediators such as IL-10, TGF-β and FoxP3 were downregulated at late stages by the primary infection with F. hepatica." (PMID 36627694, 2023). "We sought to evaluate the effect of endodontic-causative microorganisms of primary infections on mononuclear cells such as CD14+, CD4+, CD8+, CD19+ and Tregs Foxp3+." (PMID 38069174, 2023). "AWA-induced Th2 cytokine and Foxp3 expression remained significantly elevated to week 8 post infection." (PMID 37837930, 2023).
infection (continued). "F. hepatica-infected sheep and goats showed expansion of T regulatory cells (Treg) Foxp3+ during early and late stages of infection in the liver and hepatic lymph nodes." (PMID 38149297, 2023). "WT mice also display increased FoxP3+ cell frequencies amongst CXCR5+CD44+CD4+ T cell populations one week post infection compared to μMT animals, suggesting B cells promote TReg development amongst CXCR5+CD44+CD4+ T cells during Brucella infection." (PMID 37721965, 2023). "In infection, some pathogens can suppress immune responses by expanding FOXP3 + T cells, impeding immunopathological injury and limiting protective immunity." (PMID 37296126, 2023). "Similar to our findings in μMT mice, by two weeks post infection co-transfer of B cells enhanced FoxP3 expression and diminished T-bet expression on CD44+CD4+ T cells." (PMID 37721965, 2023). "In contrast, there was a significantly higher percentage of FoxP3+ Tregs in aged lungs when compared to young at days 7 and 9 post‐infection." (PMID 34962049, 2022). "In the D+Q treated group, the percentage of FoxP3 expressing Treg cells is significantly reduced on day 12 post‐infection as compared to vehicle treated." (PMID 34962049, 2022). "On the other hand, a smaller number of CD4+ICOS+Foxp3+ cells and reduced amount of IL-10 were observed during the infection with P. chabaudi and P. yoelii 17XNL." (PMID 35109868, 2022). "CLA also increased the expression of interleukin-10, transforming growth factor (TGF)-β, and inducible nitric oxide synthase (iNOS) (P<0.05), while infection elevated the expression of Foxp3, with a peak at 40 days post-infection (P<0.05)." (PMID 36544518, 2022). "A similar trend was found for transcription factors related to T- and B-cell proliferation in the lymph nodes, indicating markedly increased ROXγt, Foxp3, and T-bet since day 6 after infection in HVEM−/− mice compared with WT C57BL/6 mice." (PMID 35632787, 2022). "Our team has recently reported that early ART initiation at four days post-infection can normalize CD39+ FoxP3+ CD8 T-cell frequencies in blood and mesenteric lymph nodes of progressor SIV-infected RMs." (PMID 35967314, 2022). "A remarkable increase in the expression of CD4+ICOS+Foxp3+ regulatory T cells on 10th day post infection was observed during lethal (P. berghei and P. yoelii 17XL) infection." (PMID 35109868, 2022). "CD25+Foxp3+ Tregs were expanded across all tissues at later infection phases, but with the most statistically robust expansion (both proportional and numerical) within the liver." (PMID 35958580, 2022). "FOXP3, which reduces neuroinflammation and regulates the infection process, is responsible for the stability of Treg cells." (PMID 35266286, 2022). "The increase in this population of FOXP3+ cells directly correlates with increased inflammation in the context of infection response." (PMID 35821823, 2022). "Foxp3 is exclusively produced by Treg cells, which perform an important immune-suppressing role during infection." (PMID 34209407, 2021). "In this study, we evaluated the expressions of different TFs (T-bet, GATA3, FOXP3, and EOMES) through RT-qPCR and the associated cytokine profiles during infection with PRRSV-1 strains of different virulence in target organs." (PMID 34956200, 2021). "Further, mice treated with either an AHR antagonist or a TDO2 antagonist had fewer FoxP3+ Tregs in the lungs following infection." (PMID 33491663, 2021). "We found that TH1 (CD4+ CD44+ FoxP3- Tbet+) cells were the predominant CD4 T-cell subset during UgCl233 infection, ranging from 20% - 48% of activated CD4 T-cells." (PMID 35186781, 2021). "Further, when Foxp3-expressing cells are depleted prior to infection with Heligmosomoides polygyrus, host animals lose more weight and have worsened pathology associated with high levels of IFN-γ production." (PMID 34237106, 2021).
infection (continued). "Along with this increase in the frequency of CD44+ memory T cells, mice from CC-RIX lines with low viral titers at day 2 post-infection had a significantly increased frequency of baseline splenic Foxp3+ regulatory T cells (Treg)." (PMID 33513210, 2021). "The severe infection itself also stimulated CD3Ɛ+CD4+CD25+Foxp3+ Tregs in the spleen cells from septic mice (CLP+PBS), but the increase of Tregs is more significant after treatment with Ts-AES." (PMID 33842398, 2021). "The percentages and total numbers of CD4+CD25+Foxp3+ T cells diminished within three weeks of infection in animals treated with anti-IL-2 mAb." (PMID 34869064, 2021). "The percentages and total numbers of CD4+CD25+Foxp3+ T cells diminished within three weeks of infection." (PMID 34869064, 2021). "In summary, analysis of immune checkpoints revealed distinct expression patterns by Foxp3+ Treg and Foxp3− T cells during infection and already by trend under steady state conditions." (PMID 33452272, 2021). "This is associated with neonatal Foxp3− CD4+ T cells possessing a significantly increased capacity to produce IL-2 both before and after infection." (PMID 34665220, 2021). "Upregulation of PD-L1 by macrophages and of PD-1 by CD4+, CD8+ T and Tregs IL-10+Foxp3+ upon infection was also observed." (PMID 33776999, 2021). "Studies in P. falciparum have shown that CD25+CD127+FoxP3+ Tregs that are induced in response to infection can suppress TH1 cell function in an antigen-specific manner." (PMID 34128836, 2021). "Our data showed that upon anti-IL-2 mAb administration, mice had fewer CD4+CD25+Foxp3+ T cells at day 21 post-infection." (PMID 34869064, 2021). "In conclusion, our study shows that persistent HBoV1 infection is associated with suppression of tonsillar cytokine responses, especially transcription factors RORC2 and FOXP3." (PMID 34435757, 2021). "Mice with NK cell depletion had a significantly higher proportion of CD4+CD25+Foxp3+ T cells (Tregs) than control mice at day 3, and this enhanced frequency of Tregs were persisted till day 7 after secondary infection in both spleen and lung tissues." (PMID 32626664, 2020). "Upon OPC infection, we found that both the frequency and number of Foxp3+ cells increased in both the groups, but at significantly higher levels in aged mice than in young mice." (PMID 33240286, 2020). "G2-S16 PCD is highly active against HIV, preventing the infection of Treg, and is able to protect Treg from Foxp3 down regulation induced by HIV infection." (PMID 33321835, 2020). "Quantification of mRNA induction of FoxP3 during infection, yielded similar results, with only a significant increase in B6 mice treated with rIL-33 (Mann-Whitney test: U = 3, P < 0.01)." (PMID 32571430, 2020). "As a positive control, in one group of MFYcre mice, we intraperitoneally injected 1 x 106 CD4+CD25+GFP+ Tregs from wild-type (WT) Foxp3-GFP reporter mice or CD4+CD25+ Tregs from congenic CD45.1 mice 2 weeks prior to the infection." (PMID 33240286, 2020). "Using infection experiments we show that intraperitoneally injected metacestode tissue expands host Foxp3+ Treg, confirming the expansion of this cell type in vivo during parasite establishment." (PMID 32457746, 2020). "infection raise expression of FOXP3+ Tregs, which were generally found to be more frequent in inflammation than in healthy tissues and controls." (PMID 32153025, 2020). "High levels of FoxP3+CD4+ T cells are present in the CNS of virus-infected mice as early as 3 d after infection." (PMID 33086489, 2020). "Ex vivo S47 mouse splenocytes infected with Lm show greater numbers of CD25+, CD4+, FoxP3-Hi Tregs, 24 h post infection." (PMID 31980600, 2020). "The number of CD4+CD25+FoxP3+ Tregs was lower in Cse−/− mice lungs at 2 weeks post-infection compared to WT, which was reversed after 4 weeks of infection, suggesting that Cse−/− mice can better control pro-inflammatory immune responses at later time points." (PMID 33330130, 2020).
infection (continued). "Although IL-1β is a conventional pro-inflammatory cytokine, our study unveils an unexpected and surprising role of this cytokine in inducing functionally robust Foxp3+ cells, namely Treg17 cells, during the early phases of infection." (PMID 33240286, 2020). "At all post-infection times assayed, a reduced presence of Treg cells was here observed in line with reduced Foxp3 mRNA detected and the low levels of IL-10, TGF-β and IL-35, cytokines involved in the suppressive activity of this T cell subpopulation." (PMID 32647342, 2020). "In contrast to the constant level of Foxp3+ Treg at the later phase of infection, the induction of Foxp3 was upregulated in CD4cre; gp130loxP/loxP mice." (PMID 33375150, 2020). "To this end, we isolated bulk Tregs from naive or LCMV-experienced Foxp3-GFP reporter mice >30 days after the primary infection and adoptively transferred 5 × 105 Tregs into separate groups of naive, congenically marked recipient mice." (PMID 32433493, 2020). "In our study, the FoxP3 marker was downregulated during infection and presented a tendency to increase in the S + V group." (PMID 32517744, 2020). "FoxP3+ regulatory T cells (Tregs) control inflammation and maintain mucosal homeostasis, but their functions during infection are poorly understood." (PMID 32457450, 2020). "To validate IL-1β effects in vivo, we orally infected WT and IL-1R1-/- mice with CA and examined Foxp3+ cells in MOIL three days after infection and in vitro restimulation." (PMID 33240286, 2020). "TLR9 and FoxP3 were up-regulated in dog skin at the early stages of infection and in lymph nodes and significant downregulation of TLR3, TLR4, TLR9, IL-17, IL-22, and FoxP3 transcription was found associated with disease progression." (PMID 33352885, 2020). "The role of regulatory T cells (Tregs), especially Foxp3+ Tregs, was investigated after TB challenge infection." (PMID 31281230, 2019). "Here, we have focused on a selection of immune genes, IDO1, IFN-γ, TGF-β1 and FoxP3, to examine the regulatory immune response during C. trachomatis single versus repeated infection and post antibiotic treatment, in a cohort of a previously published study." (PMID 30832593, 2019). "Third, the percentage of SIV-specific tetramer+ CD8+ T cells in follicular areas that expressed Foxp3 was significantly higher during early infection than chronic infection in both follicular and extrafollicular areas." (PMID 30897187, 2019). "Lastly, the ratios of Tet+ cells: Foxp3+ cells in both follicular and extrafollicular regions were significantly lower in early infection compared to chronic infection." (PMID 30897187, 2019). "In this study, we measured the expression levels of IDO1 and immune regulatory markers, transforming growth factor β1 (TGF-β1) and forkhead box P3 (FoxP3), in vaginal swab samples of C. trachomatis-infected women, with either single or repeated infection." (PMID 30832593, 2019). "In contrast, the ability of CD4+Foxp3+ Tregs to migrate to CXCR3 chemokines decreased significantly with infection." (PMID 30915078, 2019). "Previously, we observed there are significant increases in the frequency and number of CD4+Foxp3+ Tregs during acute P. chabaudi AS infection in B6 mice followed by a transient decrease until the infection is resolved." (PMID 30915078, 2019). "To verify that CCR4 expression is induced in Treg throughout CVB5 infection, we analyzed Foxp3+ cells in the PLNs on days 0, 7 and 14 post-infection." (PMID 31611578, 2019). "We also determined if CXCR3 and T-bet are co-expressed on effector CD4+Foxp3− T cells and CD4+Foxp3+ Tregs during infection." (PMID 30915078, 2019). "The frequency and number of CD4+Foxp3+ cells expressing T-bet also increased during infection albeit to lower levels than effector CD4+ T cells expressing T-bet." (PMID 30915078, 2019).
infection (continued). "MLN cell populations were analyzed by flow cytometry at 14 and 28 days post-infection, and similar increases in Foxp3+ Treg numbers were seen in both wild-type and MIF−/− mice infected with H. polygyrus." (PMID 31708913, 2019). "For example, during infection, a proper cellular response against foreign pathogens requires rapid downregulation of Treg cell number and function and the ubiquitination of Foxp3 is a signal for a rapid Treg cell switch-off." (PMID 32117202, 2019). "The study reveals that the percentage of CD4+CD25+ and CD4+ FoxP3+ T cells were progressively enhanced until 4 months of infection compared to control naïve mice." (PMID 31031744, 2019). "In contrast, an increased expression of several mediators of adaptive immune responses, including IL13, TGFβ, and IFNγ, and the transcription factor forkhead box P3 (Foxp3) can be found already at the beginning of demyelination at 30 days post infection." (PMID 30669615, 2019). "For example, inhibited infection through in vivo depletion of CD4 + -FOXP3+ T Regulatory and Th17 subset populations, and aided in clearance of persistent H. pylori colonization." (PMID 31138331, 2019). "In a separate study, IL-2 treatment of NHP in early-stage infection expanded Foxp3+ Tregs, and CD4+/CD8+/γδ T effector cells." (PMID 31572365, 2019). "It is reported that Foxp3+ regulatory T cells can act against immune responses induced by infection, and the TGF β pathway takes apart in the parasite-driven inhibition of host immunity." (PMID 31790412, 2019). "In our primary infection model, the late infection was characterized by a strong Foxp3 expression and weak expression of most mediators, suggesting that their production is suppressed by Tregs." (PMID 30037796, 2018). "Our results above show that the susceptibility to infection, the magnitude of inflammation and the number of CD4+Foxp3+ cells in the lungs are dependent on CCR4." (PMID 30584243, 2018). "Fork head protein 3 (Foxp3), a marker for regulatory T cells, was significantly downregulated following infection with male only cercariae (group m) in comparison to the others." (PMID 29743881, 2018). "Infection results in the percentage of CD8+CD25+Foxp3+ cells falling from 39.5% of all CD8+CD25+ cells in the CSF of EAE mice to 30.1% and from 95.7% of all CD8+CD25hi cells in the CSF of EAE mice to 82.5%." (PMID 28975357, 2018). "CCR4−/− mice exhibited a lower frequency of CD4+Foxp3+ cells in the early (15 days), initial (30 days), and chronic (70 days) phases of infection than their respective WT counterparts." (PMID 30584243, 2018). "In the present study, we show that Foxp3+ Treg cells in secondary lymphoid organs constitutively express IL-4Rα and up-regulate the receptor expression upon S. mansoni (Sm) infection." (PMID 30379806, 2018). "CCR4−/− mice exhibited a lower frequency of CD4+Foxp3+ cells at 15, 30, and 70 days of infection than their wild-type counterparts." (PMID 30584243, 2018). "The main findings of the study were that, during active infection, peripheral and colonic FOXP3 expression was significantly raised in both the Treg counterparts (CD25+ and CD25-) in ITB patients as compared to CD as well as UC patients." (PMID 29489879, 2018). "There was no significant distinction in spite of a progressive decrease in the number of CD4+CD25+FoxP3+ Tregs 2 weeks after infection with L3 among the mice treated with PAS-5 (P > 0.05), while it was increased at 3 weeks compared with those of the control." (PMID 29843794, 2018). "Our results are consistent with these observations and demonstrate that treatment with RvD2 reduces the frequency of CD4+ T-cells and Foxp3+CD4+ Treg cells in the gingiva 6 weeks after infection." (PMID 29922275, 2018). "To address that, we traced back the source of the produced cytokines during Sm infection by co-staining of intracellular cytokines and Foxp3 in CD4+ T cells." (PMID 30379806, 2018).